PAX2 (paired box 2)
Diseases named in the same sentence as PAX2 in open-access papers (continued):
Sharing a sentence is not in itself a finding about the gene and the disease.
endometriosis (2 papers, 2022 to 2025). The growth of functional endometrial tissue in anatomic sites outside the uterine body. "SMBT with endometriosis in this study showed similar expression patterns of PAX2 and PAX8 with those in endometrioid tumors, in contrast to SMBT without endometriosis." (PMID 35387670, 2022). "Only a few cases of ovarian SMBT with endometriosis showed expression of PAX2 and conversely, most of the cases showed expression of PAX8." (PMID 35387670, 2022). "For example, 1 case of PAX2-aberrant adenocarcinoma was associated with nonatypical endometriosis similarly characterized by PAX2 loss." (PMID 39078313, 2025). "One of 5 cases (20%) of endometriosis with atypia was marker-aberrant (both PAX2 and PTEN), supporting prior findings that some cases of flat atypia may represent bona fide precursor lesions." (PMID 39078313, 2025). "PAX2 loss occurred in 1 case of nonatypical endometriosis and 1 case of EA." (PMID 39078313, 2025). "The finding of similar patterns of marker aberrancy in endometriosis adjacent to EBT and adenocarcinoma, or EBT adjacent to adenocarcinoma, further cements a link between aberrancy for β-catenin, PAX2, PTEN, and cancer initiation/progression in ovarian endometriosis-associated neoplasia." (PMID 39078313, 2025). "Just 1/32 (3%) of cases of nonatypical endometriosis was marker-aberrant, and this case was aberrant only for PAX2." (PMID 39078313, 2025). "Eleven of 22 (50.0%) patients without endometriosis showed positive PAX2 expression, while eight of 36 (22.2%) patients with endometriosis showed positivity (P = 0.016)." (PMID 35387670, 2022). "PAX2 was similarly aberrant across all components (benign, EBT, adenocarcinoma) (not shown) strongly arguing for an origin in this adjacent endometriosis." (PMID 39078313, 2025). "In immunohistochemical patterns, there was a statistically significant difference in PAX2 and PAX8 expression between in ovarian SMBT with or without endometriosis (P = 0.016, P < 0.001)." (PMID 35387670, 2022). "There was a difference in PAX2 and PAX8 expression between in ovarian SMBT with or without endometriosis." (PMID 35387670, 2022). "In conclusion, only a few cases of ovarian SMBT with endometriosis showed expression of PAX2 and conversely, most of the cases of ovarian SMBTs with endometriosis showed expression of PAX8 in contrast to SMBTs without endometriosis." (PMID 35387670, 2022). "In our study, a few cases of SMBT with combined endometriosis showed positive expression of PAX2 and most cases showed positive expression of PAX8 in contrast to SMBTs without endometriosis." (PMID 35387670, 2022). "The exact mechanism explaining how endometriosis is related to the development or progression of ovarian SMBT is not clarified yet, however, it has become clear that Müllerian markers such as PAX2 and PAX8 show distinctively different expression pattern between SMBTs with and without endometriosis." (PMID 35387670, 2022).
glomerulosclerosis (2 papers, 2012 to 2021). A hardening of the kidney glomerulus caused by scarring of the blood vessels. "Furthermore, the re-expression of Pax-2 in conjunction with WT1 in human podocytes may serve as a forerunner to a recapitulation of developmental paradigms leading to podocyte de-differentiation in glomerulosclerosis." (PMID 23029522, 2012).
gout (2 papers, 2019 to 2020). A condition characterized by painful swelling of the joints, which is caused by deposition of urate crystals. "RCS has been reported to be associated with hyperuricemia and gout in two unrelated families and the finding of the PAX2 Gly76Arg mutation in the family with FJHN prompted an ophthalmological examination of the proband (II.1)." (PMID 32776440, 2020). "These relatively rare phenotypes were also found in our study, whereas gout was firstly reported as the onset symptom of PAX2‐related disorder, and clinicians should consider PAX2‐related disorder in children with gout accompanied with unexplained impaired kidney function." (PMID 31060108, 2019).
IgA nephropathy (2 papers, 2015 to 2023). "In contrast to the genetic diagnosis of FSGS type 7 caused by a mutation in the PAX2 gene inherited from her father, the findings of the biopsy showed IgA nephropathy." (PMID 37628926, 2023). "However, the four patients without PAX2 mutations did not have FSGS, two had glomerulomegaly, and one each had IgA nephropathy or minimal change nephrotic syndrome." (PMID 26571382, 2015).
lymphoma (2 papers, 2009 to 2020). A malignant (clonal) proliferation of B- lymphocytes or T- lymphocytes which involves the lymph nodes, bone marrow and/or extranodal sites. "All 14 lymphoma cell lines expressed an undescribed PAX2 splice variant containing the entire intron 9 sequence and the exon 10 sequence." (PMID 19467152, 2009). "PAX2 is usually only expressed during embryogenesis in humans, but expression of PAX2 has been found in cell lines of human lymphoma and other cancer types, where it promotes cell growth and survival." (PMID 32857815, 2020).
mediastinal tumours (2 papers, 2024 to 2025). "HN-PG and the suspected non-chromaffin mediastinal tumours had low expression of the chromaffin cell marker CARTPT24, neural transcriptional regulators (TFAP2B, TOX3, GATA3, POU4F, NEUROG2, PAX2), HOX genes (HOXA1-10, HOXB4, HOXB6-9, HOXC4-HOXC13), and the long non-coding RNA HOTAIR." (PMID 40097403, 2025). "HN-PG and the suspected non-chromaffin mediastinal tumours had low expression of the chromaffin cell marker CARTP24, neural transcriptional regulators (TFAP2B, TOX3, GATA3, POU4F, NEUROG2, PAX2), HOX genes (HOXA1–10, HOXB4, HOXB6–9, HOXC4-HOXC13), and the long non-coding RNA HOTAIR." (PMID 38978571, 2024).
Nephropathy (2 papers, 2023 to 2024). A nonspecific term referring to disease or damage of the kidneys. "A 7-year-old child with nephrotic range proteinuria was found to have PAX2-associated nephropathy, according to a recent study." (PMID 37628926, 2023).
nephrosis (2 papers, 2021 to 2025). Pathological processes of the KIDNEY without inflammatory or neoplastic components. "Twenty different PAX2 pathogenic variants were identified in 32 individuals (27 families) with a diagnosis of RCS, CAKUT and nephrosis from the Chinese cohort." (PMID 34696790, 2021). "Combined with phenotypes and genotype, the final diagnosis of RCS was established in 9 patients, PAX2-related CAKUT was identified in 11 patients and PAX2-related nephrosis was identified in 12 patients." (PMID 34696790, 2021).
PEComas (2 papers, 2016 to 2025). "These tumors can be excluded by immunohistochemistry, as PEComas and melanotic Xp11.2 translocation cancer are negative for renal cell markers (CD10, PAX2 and PAX8) and positive for MelanA and HMB45." (PMID 27733182, 2016).
prostatic adenocarcinoma (2 papers, 2023 to 2025). "PAX2 transcriptional silencing in EC is comparable to ERG transcriptional upregulation in prostatic adenocarcinoma, which is strikingly similar to EC." (PMID 40829174, 2025).
rhabdomyosarcoma (2 papers, 2024 to 2025). A rare aggressive malignant mesenchymal neoplasm arising from skeletal muscle. "PAX2 is a similar protein, but it is more likely positive in malignant mesenchymal tumors including rhabdomyosarcoma and synovial sarcoma, so PAX2 must be cautiously used to differentiate between sarcomas and sarcomatoid RCCs." (PMID 38297323, 2024). "PAX3 and PAX7 chromosomal translocations define childhood rhabdomyosarcomas, raising the possibility that PAX2 gene rearrangements or deletions might analogously underpin PAX2 expression loss in EC." (PMID 40829174, 2025).
Ureteral obstruction (2 papers, 2018). Obstruction of the flow of urine through the ureter. "To examine whether ureteral obstruction was caused by existence of xenogeneic cells in nephric duct during the development, we generated interspecies chimera by injection of Pax2 and Pax8 double knockout ES cells into Rat blastocyst." (PMID 30327488, 2018). "In vivo, Wistar rats (n = 36) were subjected to unilateral ureteral obstruction (UUO) (n = 18) or sham surgery (n = 18), with tissues from post-operative day 3, 7, and 14 days examined, and PAX2/ADAM10 activity measured." (PMID 30117015, 2018). "Urine flow testing revealed that no ureteral obstruction was observed in Pax2 and Pax8 double mutant ESCs injected interspecies chimera." (PMID 30327488, 2018). "We previously observed that PAX2 was reactivated in renal tubular epithelial cells in a rat model of unilateral ureteral obstruction (UUO); moreover, PAX2 could induce EMT in vitro in tubular epithelia." (PMID 30117015, 2018).
urothelial carcinoma (2 papers, 2013 to 2024). A malignant neoplasm derived from the transitional epithelium of the urinary tract (urinary bladder, ureter, urethra, or renal pelvis). "Positive immunoreaction for HNF and PAX8 (or PAX2) helps exclude non-CCA types of urothelial carcinoma." (PMID 24455377, 2013).
acrorenal syndrome (1 paper, 2025). "OMN can be classified as isolated or associated with congenital anomalies in conditions such as WHS, PAX2 mutations, and acrorenal syndrome." (PMID 41225980, 2025).
acute myeloid leukemia (1 paper, 2009). Acute myeloid leukemia (AML) is a group of neoplasms arising from precursor cells committed to the myeloid cell-line differentiation. "In breast and prostate cancers as well as in acute myeloid leukemia (AML) a correlation with WT1 expression has been observed, suggesting that PAX2 is a positive transcriptional regulator of WT1." (PMID 19467152, 2009).
Age-related cataract (1 paper, 2021). A type of cataract (opacification of the lens) that forms during the course of aging. "A non-coding risk allele for age-related cataract (rs6603883) located in a paired-box-2 (PAX2) binding-site within the EPHA2 gene promoter suggested that it acts by down-regulating EPHA2 expression in cultured lens cells." (PMID 34685586, 2021).
Ataxia (1 paper, 2012). Ataxia refers to impaired coordination of voluntary muscle movement. "Using three measures of gait performance, the Pax2-Cre N-Myc CKO mice suffered from severe ataxia that did not improve with time suggesting functional input and partial compensation." (PMID 24710525, 2012).
Camptodactyly (1 paper, 2019). The distal interphalangeal joint and/or the proximal interphalangeal joint of the fingers or toes cannot be extended to 180 degrees by either active or passive extension. "Only one child had previously been reported with a PAX2 mutation and a skeletal deformity (congenital camptodactyly) (Liu, Wang, Huang, & Yu, 2018)." (PMID 31060108, 2019).
Cervical tumor (1 paper, 2025).
cholecystolithiasis (1 paper, 2022). Single or multiple, ovoid or irregular, solid particles that are formed from bile, cholesterol, and calcium in the gallbladder cavity. "Furthermore, we also reported several novel manifestations of PAX2 variants, including cholecystolithiasis and testicular dysgenesis." (PMID 35444690, 2022).
congenital nephrotic syndrome (1 paper, 2024). "Most of the genes commonly associated with congenital nephrotic syndrome have reported ocular manifestations (NPHS1, NPHS2, WT1, LAMB2, PAX2, PLCE1)." (PMID 37578539, 2024).
cystinosis (1 paper, 2022). Cystinosis is a metabolic disease characterized by an accumulation of cystine inside the lysosomes, causing damage in different organs and tissues, particularly in the kidneys and eyes. "As previous studies characterized kidney progenitor cells as being PAX2+/CD133+, we performed immunochemistry on the kidney tissue of one nephropathic cystinosis patient by use of these markers." (PMID 35406807, 2022). "Being able to examine only a single historic cystinosis kidney specimen, we demonstrated cells co-expressing CD133+/PAX2+ scattered through the tubular epithelium and the parietal epithelium of the Bowman’s capsule." (PMID 35406807, 2022).
endometrial endometrioid carcinoma (1 paper, 2022). "PAX2 is proposed to possess a clinical-predictive role in endometrial endometrioid carcinoma." (PMID 35028121, 2022).
esophageal cancer (1 paper, 2018). A primary or metastatic malignant neoplasm involving the esophagus. "For example, increasing levels of PAX2 expression have been linked to metastatic progression in esophageal cancer." (PMID 29928489, 2018).
fallopian tube carcinoma (1 paper, 2011). A carcinoma that arises from epithelial cells of the fallopian tube. "The role of PAX2 in primary fallopian tube carcinomas (PFTC)/PPSC is yet to be defined." (PMID 21826275, 2011).
fibrosis (1 paper, 2020). the formation of excess fibrous connective tissue in an organ or tissue in a reparative or reactive process. "Fibrosis, histopathological features, serum creatinine (sCr), BUN, and renal mRNA expression of αSMA, Col-1α, TGF-β1, CTGF, BMP7, IL-1, TNFα, VEGF and PAX2 were analyzed." (PMID 33275619, 2020).
gallstones (1 paper, 2025). Solid crystalline precipitates in the biliary tract, usually formed in the gallbladder, resulting in the condition of cholelithiasis. "With the growing body of research on PAX2, additional associations have been discovered, including gallstones and testicular hypoplasia." (PMID 40948392, 2025).
glioma (1 paper, 2021). A benign or malignant brain and spinal cord tumor that arises from glial cells (astrocytes, oligodendrocytes, ependymal cells). "HOX genes and PAX2 were not expressed at levels detectable by RNA-seq or qPCR analysis in GPC16 cells (data not shown), indicating that the expression of certain development-related transcription factors may vary between cell lines and primary cells, or generally between glioma cells." (PMID 34381018, 2021).
head and neck carcinoma (1 paper, 2023). A carcinoma that arises from the head and neck region. "In this figure, SIX1 represents the SIX family, and there were no data regarding PAX2 and SALL1 in head and neck carcinoma according to the TCGA database." (PMID 36983712, 2023).
Hyperglycemia (1 paper, 2020). An increased concentration of glucose in the blood. "To rule out the effects of hyperglycemia on OHC viability and to obtain more understanding of the genetic background effect, we generated Manfflox/flox;Pax2-Cre cKO mice where Manf is inactivated in the epithelial cells and neurons of the inner ear21." (PMID 32029702, 2020).
influenza infection (1 paper, 2013). "We observed PAX2, a transcription factor, to be significantly upregulated upon influenza infection and its expression could be modulated by regulating miR-26a." (PMID 24116168, 2013).
Intellectual disability (1 paper, 2020). "PAX2 is expressed in other tissues (e.g., cerebellum, hypothalamus otic vesicle, genitourinary tract, and pancreas), and additional features of RCS include CNS anomalies, intellectual disability and elevated pancreatic amylase." (PMID 32776440, 2020).
intraepithelial carcinomas (1 paper, 2025). "In the case of EA with PAX2 loss, the biological significance of PAX2 loss is substantiated by concurrent PTEN loss/aberrancy, providing further evidence that a subset of EA may be significant precursor lesions (ie, intraepithelial carcinomas)." (PMID 39078313, 2025).
Kabuki syndrome (1 paper, 2018). Kabuki syndrome (KS) is a multiple congenital anomaly syndrome characterized by typical facial features, skeletal anomalies, mild to moderate intellectual disability and postnatal growth deficiency. "Moreover, an overlap has been described of clinical features with many other diseases, such as 22q deletion syndrome, Kabuki syndrome, Kallmann syndrome, retinoic acid embryopathy, VACTERL association and PAX2 abnormalities." (PMID 29434620, 2018).
Kaposi's sarcoma (1 paper, 2013). A malignant neoplasm characterized by a vascular proliferation which usually contains blunt endothelial cells. "Increased expression of PAX2 gene and protein was associated with enhanced resistance to apoptosis in Kaposi sarcoma–associated herpesvirus infected cells." (PMID 24116168, 2013).
liver dysfunction (1 paper, 2025). "Additionally, we observed two rare extrarenal manifestations – right-sided hydrocele and liver dysfunction – which may expand the phenotypic spectrum of PAX2-related disorders." (PMID 40948392, 2025).
membranous nephropathy (1 paper, 2019). "The remaining findings (oligomeganephronia combined with atypical membranous nephropathy, and mesangial proliferative glomerulonephritis) may be due to the younger age at renal biopsy or the diversity of pathological results with PAX2 mutation, some of which have been reported." (PMID 31060108, 2019).
mesonephric adenocarcinoma (1 paper, 2025). An adenocarcinoma of the cervix or the vagina arising from mesonephric remnants. "Mesonephric adenocarcinoma characteristically expresses mesonephric markers such as GATA3, TTF1, and PAX2, while lacking hormone receptor expression." (PMID 40647429, 2025).
mesonephric tumors (1 paper, 2021). "PAX2 is a protein associated with the development of the Wolffian system and is typically expressed in mesonephric tumors." (PMID 34441384, 2021).
non-small cell lung carcinoma (1 paper, 2020). A group of at least three distinct histological types of lung cancer, including non-small cell squamous cell carcinoma, adenocarcinoma, and large cell carcinoma. "MiRNA-7-5p inhibits cell growth, induces cell cycle arrest and cell apoptosis via modulating Paired Box 2 (PAX2) in non-small cell lung cancer (NSCLC)." (PMID 32782028, 2020).
oncocytoma (1 paper, 2013). "Using a 10% immunoexpression cut-off, Pax-2 immunoreactivity discriminated chrRCC from oncocytoma with 67% sensitivity and 90% specificity." (PMID 23890189, 2013). "PAX2 mRNA expression was significantly lower in chrRCC, compared to ccRCC, pRCC and oncocytoma, and transcript levels correlated with immunoexpression." (PMID 23890189, 2013). "The differences in Pax-2 expression between pRCC and ccRCC on one hand, and chrRCC and oncocytoma, on the other, may be related with the site of origin of each tumour type and may, thus, reflect distinct carcinogenic pathways." (PMID 23890189, 2013). "However, the highest levels were observed in pRCC and ccRCC, whereas oncocytomas showed intermediate levels, and chrRCCs displayed the lowest levels of PAX2 mRNA." (PMID 23890189, 2013). "Because the morphological differential diagnosis between chrRCC and oncocytoma might be troublesome, we tested whether Pax-2 immunostaining might be used as an ancillary tool for histopathological assessment." (PMID 23890189, 2013). "We concluded that Pax-2 expression might be used as an ancillary tool to discriminate chrRCC from oncocytomas with overlapping morphological features." (PMID 23890189, 2013). "Hypothetically, oncocytomas retain the normal Pax-2 expression patterns." (PMID 23890189, 2013). "Indeed, the best Pax-2 immunostaining cut-off value for discriminating between chrRCC and oncocytoma was 10%, with a sensitivity and specificity of 67% and 90%, respectively." (PMID 23890189, 2013). "Pax-2 is commonly expressed in the most prevalent renal cell tumour (RCT) subtypes—clear cell RCC (ccRCC), papillary RCC (pRCC) and oncocytoma—but not in chromophobe RCC (chrRCC), which frequently displays chromosome 10 loss (to which PAX2 is mapped)." (PMID 23890189, 2013). "Indeed, significant Pax-2 protein expression has been found in three of the most prevalent RCT subtypes—clear cell RCC, papillary RCC and oncocytoma—but not in chromophobe RCC." (PMID 23890189, 2013). "Finally, diffuse protein expression of Pax-2 has been reported to be frequent in three of the most prevalent RCT subtypes - ccRCC, pRCC and oncocytoma - but not in chrRCC, suggesting its use for differential diagnosis in problematic cases." (PMID 23890189, 2013).